LGALS3 (galectin 3)
Diseases named in the same sentence as LGALS3 in open-access papers (continued):
Sharing a sentence is not in itself a finding about the gene and the disease.
hyperthyroidism (1 paper, 2024). Overactivity of the thyroid gland resulting in overproduction of thyroid hormone and increased metabolic rate. "The clustering labels for the journals were ultrasound, ultrasonography, galectin-3, thyroidectomy, hyperthyroidism, and radio-guided surgery." (PMID 37608676, 2024).
hyperuricemia (1 paper, 2022). An abnormally high level of uric acid. "Hyperuricemia is characterized by an increase in inflammation markers such as C-reactive protein (CRP), fibrosis markers such as galectin-3 (Gal-3) and carboxy-terminal telopeptide of type I collagen (CITP)." (PMID 35216477, 2022).
Hypoalbuminemia (1 paper, 2022). The concentration of albumin in the blood circulation is below the lower limit of normal. "We also identified hypoalbuminemia as a common characteristic among critically ill patients which was negatively correlated with galectin-3." (PMID 35115644, 2022).
hypopharyngeal squamous cell carcinomas (1 paper, 2010). "The level of galectin-3 expression in relation to neoplastic progression of hypopharyngeal squamous cell carcinomas (HSCCs) and laryngeal squamous cell carcinomas (LSCCs) demonstrate an association between the level of galectin-3 expression and neoplastic progression in these carcinomas." (PMID 23658855, 2010).
idiopathic dilated cardiomyopathy (1 paper, 2022). Decreased function of the heart associated with cardiac enlargement and congestive heart failure, of unknown cause. "The evidence for the usefulness of galectin-3 in the assessment of such pathologies as idiopathic dilated cardiomyopathy, coarctation of the aorta, functionally univentricular heart or tetralogy of Fallot were not completely confirmed." (PMID 35410028, 2022).
IgG4-related pancreatitis (1 paper, 2017). "Among these proteins, galectin-3 levels were 13-fold higher in IgG4-related pancreatitis (P < 0.01)." (PMID 28593065, 2017).
inclusion body myositis (1 paper, 2025). A slowly progressive degenerative inflammatory disorder of skeletal muscles characterized by late onset weakness of specific muscles and distinctive histopathological features. "One study identified six macrophage subpopulations, including Spp1‐ and Lgals3‐expressing subtypes in dystrophic regions of DMD mice, with human analogs detected in biopsies from patients with DMD, inclusion body myositis (IBM), and other inflammatory myopathies." (PMID 41431371, 2025).
insulin resistant diabetes (1 paper, 2015). "Galectin-3 knockout mice (KO) and wild-type mice (WT) were fed either a high-fat diet (HFD) (60 % fat calories) to produce insulin resistant diabetes, or standard chow (12 % fat calories), and their metabolic and endothelial responses were measured." (PMID 26047815, 2015).
interstitial nephritis (1 paper, 2018). Inflammation of the renal tubules and supporting tissues of the kidney. "The histopathological analysis showed an increased, mild interstitial nephritis in LIC + Lgals3−/− mice compared to LIC-infected mice, with scores of 1.02 ± 0.16 and 1.83 ± 0.31, respectively (P < 0.0001)." (PMID 30425972, 2018). "Our aim was to characterize the role of macrophages and galectin 3 (Gal-3) on the survival, clinical course, bacterial burden, interstitial nephritis, and chronic kidney fibrosis in Leptospira interrogans serovar Copenhageni (LIC)-induced experimental murine leptospirosis." (PMID 30425972, 2018).
intervertebral disc degeneration (1 paper, 2024). "Galectin-3 may affect intervertebral disc degeneration by regulating the degradation of the extracellular matrix." (PMID 38561725, 2024). "Through in vitro experiments, we also verified that low-expressed Galectin-3 could regulate cartilage endplate cell proliferation, apoptosis, and cell cycle, thus regulating intervertebral disc degeneration." (PMID 38561725, 2024). "In summary, with the progression of intervertebral disc degeneration, the expression of Galectin-3 in clinical tissues decreases, which may further promote intervertebral disc degeneration." (PMID 38561725, 2024). "It has also been suggested that Galectin-3 may have a protective effect on cells and tissues involved in intervertebral disc degeneration, limiting collagen damage and changes in biomechanical properties." (PMID 38561725, 2024). "Furthermore, the expression of Galectin-3 is upregulated in nucleus pulposus cells and inhibition of Galectin-3 can alleviate spinal cord injury and intervertebral disc degeneration." (PMID 38561725, 2024). "These indicate that Galectin-3 can affect the expression of CCL3, may play a role in the inflammatory cell infiltration of the intervertebral disc cartilage endplate, and affect the occurrence of intervertebral disc degeneration." (PMID 38561725, 2024).
inverted papilloma (1 paper, 2014). An endophytic benign papillary epithelial neoplasm that results from the invagination and proliferation of epithelial cells in the underlying stroma. "Our results suggest that galectin-3, -4, -7 and -9 could be involved in the biology of inverted papillomas." (PMID 24859692, 2014). "Indeed, epithelial overexpression of galectin-3 (P=0.0002), galectin-4 (P<10−6), galectin-7 (P<10−6) and galectin-9 (P<10−6) was observed in inverted papillomas compared to non-malignant diseases." (PMID 24859692, 2014).
Kawasaki disease (1 paper, 2022). A rare inflammatory disease characterized by an acute febrile, systemic, self-limiting, medium-vessel vasculitis primarily affecting children. "In children in the pre-treatment phase of Kawasaki disease, the plasma concentration of the galectin-3 was found to be significantly higher than in the control group." (PMID 35410028, 2022). "In Kawasaki disease, galectin-3 plasma concentration is higher in children in whom chronic inflammation drives aneurysmal changes in the coronary arteries, as compared to those patients in whom the disease takes the form of the progressive condition." (PMID 35410028, 2022).
lentivirus infection (1 paper, 2017). Virus diseases caused by the Lentivirus genus. "To investigate membrane rupture, we introduced mCherry fused to N-terminus of Galectin-3 (mCherry-Galectin-3) into H4/V1S-SV2/LAMP1-eCFP cells via lentivirus infection." (PMID 28794446, 2017).
leprosy (1 paper, 2024). Leprosy is a chronic infectious disease affecting primarily the skin and peripheral nervous system. "Monocytes in the presence of galectin-3 have a reduced antigen presentation, indicating an influence of the lectin through glucose uptake on the low immune response in leprosy patients." (PMID 39308868, 2024).
leptospirosis (1 paper, 2018). A contagious bacterial infection caused by spirochetes of the genus Leptospira. "In order to study the role of Gal-3 in experimental murine leptospirosis, C57BL/6J Lgals3−/− and their control littermate mice were used in a comparative study." (PMID 30425972, 2018).
Lewis lung carcinoma (1 paper, 2017). "JAG1 overexpression in Lewis lung carcinoma cells accelerated tumor growth in vivo, but this effect was prevented in Lgals3−/− mice." (PMID 28533486, 2017). "Lewis lung carcinoma cells (LLC) were transduced with an empty vector retrovirus (LLC-EV), JAG1-encoded retrovirus (LLC-JAG1) or DLL4-encoded retrovirus (LLC-DLL4) and implanted subcutaneously into C57black/6 Lgals3+/+ or Lgals3−/− mice." (PMID 28533486, 2017).
lupus-like syndrome (1 paper, 2019). "Here, we used pristane (2,6,10,14-tetramethylpentadecane) to induce lupus-like syndrome in Lgals3−/− and Lgals3+/+ BALB/c mice." (PMID 31601823, 2019).
macular degeneration (1 paper, 2021). Loss of vision in the central portion of the retina (macula), secondary to retinal degeneration. "Importantly, treatment with verteporfin, a clinical drug for macular degeneration, decreases LGALS3 expression and effectively inhibits skeletal complications of HCC." (PMID 33643786, 2021).
malaise (1 paper, 2025). A feeling of general discomfort or uneasiness, an out-of-sorts feeling. "Among clinical features, galectin-3 and sICAM-1 levels were notably higher in those with malaise (p = 0.017 for both) and myalgia (p = 0.005 and p = 0.004, respectively)." (PMID 40733621, 2025).
malignant pheochromocytoma (1 paper, 2020). "The aim of this study was to investigate the expression of Snail, galectin-3, and IGF1R in benign and malignant pheochromocytoma and paraganglioma (PPGL) and explore their role in the diagnosis of malignant PPGL." (PMID 32190664, 2020).
malnutrition (1 paper, 2021). Inadequate nutrition resulting from poor diet, malabsorption, or abnormal nutrient distribution. "Independent risk factors for elevated plasma galectin-3 and malnutrition were identified by multivariate logistic regression." (PMID 34444962, 2021). "For patients with biliary tract cancer, an increased plasma concentration of galectin-3 is associated with the risk of malnutrition." (PMID 34444962, 2021). "We next examined whether elevated galectin-3 levels could discriminate between hemodialysis patients with and without malnutrition." (PMID 34444962, 2021).
mitral valve disease (1 paper, 2022). "Serum concentrations of Galectin-3 and ST2 were not statistically different between canine patients in the respective stages of mitral valve disease or in comparison to dogs in the control group at any timepoint." (PMID 35780161, 2022). "For this purpose, serum concentrations of Galectin-3 and ST2 of 64 dogs with different stages of mitral valve disease and 21 dogs without cardiac disease were analyzed at the first examination and six months later." (PMID 35780161, 2022). "In this study, no relation between Galectin-3 and ST2 levels to the presence or stage of mitral valve disease could be detected." (PMID 35780161, 2022).
motor neuron disease (1 paper, 2012). "Although this study focuses on neuroinflammation, galectin-3 is pleiotropic and may modulate other factors involved in motor neuron disease." (PMID 23139902, 2012). "Increased galectin-3 protein was recently observed in spinal cords from SOD1G93A mice and patients with ALS, where it was also observed in CSF, and suggested that it may be a potential clinical biomarker of motor neuron disease." (PMID 23139902, 2012).
myocardial disease (1 paper, 2018). "Serum biomarkers of fibrosis also appear to be important in detecting and monitoring myocardial disease in CKD, with recent data confirming a trend with galectin-3 and GLS in HD patients." (PMID 29366457, 2018).
Myocardial necrosis (1 paper, 2017). Irreversible damage to heart tissue (myocardium) due to lack of oxygen after a heart attack (myocardial infarction). "We have not found a significant correlation between galectin-3 plasma concentration and the marker of myocardial necrosis high-sensitivity troponin I concentration, nor an association between galectin-3 plasma levels and a number of coronary arteries with significant angiographic stenosis." (PMID 29118378, 2017).
nephrolithiasis (1 paper, 2025). The presence of a calculus in the pelvis of the kidney; this is most often composed of mineral salts and proteins. "To determine whether serum Lgals3 levels are associated with kidney injury and fibrosis in human patients, we measured serum Lgals3 levels in 10 healthy participants and 10 nephrolithiasis patients." (PMID 39903812, 2025). "Then, a single‐nucleus atlas of the human nephrolithiasis database (GSE231568) was used to test the expression of Lgals3." (PMID 39903812, 2025). "Then, we evaluated the Lgals3 expression and the results showed that Lgals3 was significantly increased in the kidney of nephrolithiasis patients." (PMID 39903812, 2025). "The level of Lgals3 was elevated in nephrolithiasis patients compared with healthy participants." (PMID 39903812, 2025). "Meanwhile, to verify the clinical potential of targeting Lgals3 for treatment of kidney stones, we established another CaOx crystal mouse model according our previous studies by injecting glycolic acid for consecutively 12 days and inhibited Lgals3 through MCP and GB1107." (PMID 39903812, 2025).
neuralgia (1 paper, 2020). "The median of patients with HZN and neuralgia without HZN of age, NRS score, percentage of CD8+, CD4+/CD8+, IL-6, and galectin-3 were 63.0, 5.0, 29.0, 1.25, 49, and 1.005, respectively." (PMID 32351643, 2020).
neuroendocrine carcinoma (1 paper, 2025). A malignant neuroendocrine neoplasm composed of cells containing secretory granules that stain positive for NSE and chromogranin. "In the PTC area, Tg, Galectin-3, and CK19 are positive, while CT is negative; in the MTC area, most patients have positive CT and CEA, and neuroendocrine cancer markers such as Syn, CgA, and CD56 are mostly positive, while TG is generally negative." (PMID 41323380, 2025).
neuropathic pain (1 paper, 2026). Chronic pain caused by damage to nerve fibers. "Together these findings reveal that PTX treatment drives coordinated immune responses, and emergence of galectin-3 pro-inflammatory macrophages in DRG could be a feature of persistent paclitaxel-induced neuropathic pain." (PMID 42292309, 2026).
Newcastle disease (1 paper, 2012). A condition caused by infection by the Newcastle disease virus, which may be characterized by conjunctivitis, respiratory illness, and diarrhea. "In addition, Galectin expression is regulated by Herpesvirus 1, Newcastle disease, Epstein Barr Virus, Hepatitus C virus and Human papiloma virus (HPV) while Galectin 3 secretion and carbohydrate binding increase upon Herpesvirus 1 infection." (PMID 22428080, 2012).
Obstructive Sleep Apnea (1 paper, 2025). "However, research on the role of galectin-3 in obstructive sleep apnea is still insufficient." (PMID 39941305, 2025).
oropharyngeal squamous cell carcinoma (1 paper, 2010). "The application of the endogenous galectin-3 as a histochemical marker defines a new prognostic tool in patients with laryngeal and oropharyngeal squamous cell carcinoma." (PMID 23658855, 2010).
ovarian endometriosis (1 paper, 2024). A non-neoplastic disorder characterized by the growth of endometrial tissue in the ovaries. "This study aimed to investigate the potential role of galectin-3 (Gal-3) in the pathogenesis of fibrotic alterations in ovarian endometriosis (OVE)." (PMID 38371379, 2024).
ovarian tumor (1 paper, 2023). "Since Vδ1 T cells are enriched at the tumor site of pancreatic and ovarian tumor cells, the different impact of galectin-3 on Vδ1 T cells is of high interest and makes them attractive for γδ T-cell-based immunotherapy." (PMID 38259448, 2023). "After coculture between ovarian tumor cells and Vδ1 or Vδ2 T cells enhanced levels of galectin-3 were released." (PMID 38259448, 2023). "We observed that the different established ovarian tumor cell lines expressed intracellular galectin-3 comparable to freshly isolated ovarian tumor cells." (PMID 38259448, 2023). "As shown by a time kinetic over 72 hours, galectin-3 was released only in small amounts by either pancreatic and ovarian tumor cells (PancTuI, KI-OCp012 or OVCAR-3 cells) or by peripheral blood mononuclear cells (PBMC)." (PMID 38259448, 2023). "In parallel, the absolute cell number of viable EpCAM (CD326)-positive ovarian tumor cells is reduced compared to day 0, which underline the observation that Vδ2 T-cell cytotoxicity is not influenced by galectin-3." (PMID 38259448, 2023). "An increase of galectin-3 was measured when Vδ2 TIL were cocultured with freshly isolated autologous ovarian tumor cells compared to the culture without tumor cells." (PMID 38259448, 2023).
Patent ductus arteriosus (1 paper, 2021). In utero, the ductus arteriosus (DA) serves to divert ventricular output away from the lungs and toward the placenta by connecting the main pulmonary artery to the descending aorta. "Although heart diseases are relatively common in dogs, a few studies have analyzed the circulating galectin-3 concentration in dogs with various heart diseases, including myxomatous mitral valve disease, patent ductus arteriosus, and pulmonic stenosis." (PMID 34722704, 2021).
pericardial effusion (1 paper, 2021). Fluid collection within the pericardial sac, usually due to inflammation. "He developed cardiac diastolic dysfunction with dilated left ventricle, moderate pericardial effusion (required pericardial window on day +106) and elevated serum troponin-T and elevated galectin-3 (37.4 ng/ml)." (PMID 33614514, 2021).
postherpetic neuralgia (1 paper, 2020). "The mechanism by which galectin-3 induces postherpetic neuralgia is unclear." (PMID 32351643, 2020). "This study aims to explore the value of serum galectin-3 in patients with herpes zoster neuralgia (HZN) and postherpetic neuralgia (PHN) and other factors influencing HZN and PHN occurrence." (PMID 32351643, 2020).
retinal vein occlusion (1 paper, 2023). An occlusion of the retinal vein. "Proteins that were upregulated in our study and in experimental retinal vein occlusion included fibronectin, annexin A1, galectin-3, alpha-crystallin B chain, vimentin, annexin A2, STAT1, GFAP, osteopontin, vitronectin, and clusterin." (PMID 37175625, 2023).
Salmonella Infections (1 paper, 2025). Infections with bacteria of the genus SALMONELLA. "Further, CrARFIP2KO cells showed a reduced number of LGALS3 spots during Salmonella infection, together with an increased association of ATG9A and PI4K2A with the bacteria." (PMID 40460835, 2025).
Sandhoff disease (1 paper, 2007). A lysosomal disorder from the GM2 gangliosidosis family, caused by biallelic pathogenic variants in the HEXB gene, characterized by GM2 ganglioside accumulation in the nervous system and progressive central nervous system degeneration. "In the Sandhoff disease mouse model, microglial activation was shown to precede neurodegeneration and was associated with upregulation of macrophage markers CD68/macrosialin, galectin 3, cathepsins S and C, Mpeg1, and glycoprotein49a, which we also observed." (PMID 18021406, 2007).
Sertoli cell tumor (1 paper, 2025). A sex cord-stromal tumor of the testis or the ovary. "Galectin-3 has been discussed as a marker of aggressiveness in testicular tumors, with LGALS3 transcripts down-regulated in malignant Sertoli cell tumors, but seen increased in non-seminomatous testicular germ cell tumors." (PMID 39792160, 2025).
soft tissue tumors (1 paper, 2019). "However, the role of galectin-3 in vascular tumors or other soft tissue tumors is unknown." (PMID 31252633, 2019).
Splenomegaly (1 paper, 2023). Abnormal increased size of the spleen. "Regarding the clinical data of the patients, in the same institution, a previous study showed a significant association between splenomegaly and a relatively higher LGALS3 expression." (PMID 36861129, 2023).
squamous cell lung carcinoma (1 paper, 2024). A carcinoma arising from squamous bronchial epithelial cells. "In this exploratory analysis, galectin-3 levels were significantly lower in patients with squamous cell lung cancer (p = 0.0019) and in patients exposed to chemotherapy (p = 0.0375)." (PMID 38539500, 2024). "A recent study revealed a correlation between galectin-3 expression and squamous cell lung cancer stage." (PMID 38539500, 2024).
temporal lobe epilepsy (1 paper, 2023). A localization-related (focal) form of epilepsy characterized by recurrent seizures that arise from foci within the temporal lobe, most commonly from its mesial aspect. "As reported by Chen and his colleagues, some immune‐related gene, such as Lgals3 and Serpine1, have been identified as hub genes in human temporal lobe epilepsy." (PMID 36440924, 2023).
testicular cancer (1 paper, 2023). A primary or metastatic malignant neoplasm that affects the testis. "using immunohistochemistry and RT-PCR, analyzed galectin-3 expression in testicular cancer." (PMID 38144531, 2023).